KRAS (KRas proto-oncogene, GTPase)
Diseases named in the same sentence as KRAS in open-access papers (continued):
Sharing a sentence is not in itself a finding about the gene and the disease.
lung cancer (continued). "Although the gene remains largely untargeted, pioneering studies have elucidated the signaling cascades originating in lung cancer cells from KRAS activating mutations and have provided the medical community with novel therapeutic targets, such as the combined KRAS/NF-κB inhibition." (PMID 33494181, 2021). "In addition, an Asian cohort study analyzed the prognosis of lung cancer patients who received different chemotherapy regimens according to KRAS mutation status." (PMID 35070984, 2021). "However, the KRAS G12C mutation rate is reported to be high at 13% in lung cancer, and it is only approximately 1% in pancreatic cancer and biliary tract cancer." (PMID 33562094, 2021). "KRAS mutations occur in pancreatic, colorectal, and lung cancers." (PMID 34830757, 2021). "Additionally, it was shown that there is a high co-occurrence of KEAP1 and KRAS mutations in human lung cancers which elevates cellular rates of glutaminolysis." (PMID 31936571, 2020). "A poor prognosis of KRAS mutation patients in advanced lung cancer stages has also been reported." (PMID 32607238, 2020). "In this study, to study the functional effects of key driver KRAS mutations on gene expression in lung cancer, we analyzed the gene expression profiles of 156 lung cancer cell lines with KRAS mutations and other 3,582 lung cancer cell lines without KRAS mutations." (PMID 32117436, 2020). "Our results were helpful for understanding the roles of KRAS mutation in lung cancer." (PMID 32117436, 2020). "Therefore, the likelihood of KRAS mutations in lung cancer patients is determined by the number of years of smoking and does not significantly decrease over time after quitting." (PMID 32342665, 2020). "Therefore, the search for how the KRAS mutations affected the gene in lung cancer has been a long-standing goal in cancer biology." (PMID 32117436, 2020). "Although only a small proportion of KRAS mutation patients enrolled in the mCohort were diagnosed with stage I or II disease, KRAS mutation seems to be an early event that might drive lung cancer development." (PMID 32607238, 2020). "Other common KRAS mutations in lung cancer are G12V and G12D." (PMID 32117436, 2020). "As lung cancers harboring KRAS mutation have high response rate to PD-1/PD-L1 blockade, KRAS mutation might be a potential driver of DNA instability and DNA damage repair defects, thereby leading to the production of more neoantigens." (PMID 33194642, 2020). "The higher mutation burden of KRAS mutant lung cancer may be due to the higher proportion of smokers among the patients presenting this type of cancer." (PMID 33194642, 2020). "However, mutations of KRAS present in numerous cancer types, most frequently in pancreatic (> 60%), colorectal (> 40%), and lung cancers, drive oncogenic processes through overactivation of proliferation." (PMID 32715349, 2020). "Furthermore, SQS mRNA levels were significantly upregulated in lung cancer patients with KRAS mutations." (PMID 32862200, 2020). "Moreover, the prevalence of East Asian patients with lung cancer that have KRAS mutations is about 5%–10%, compared to ≤ 35% of Caucasian patients." (PMID 32944405, 2020). "Recent studies suggest that patients with activating mutations in KRAS may benefit from a PD-1 blockade, but the clinical experiments involved lung cancers with unclear underlying mechanisms." (PMID 33254149, 2020).
lung cancer (continued). "Similarly, IL-6 expressed by tumor-associated macrophages (TAMs) in KRAS driven lung cancer model causes activation of STAT3 pathway with tumor progression." (PMID 33352869, 2020). "However, the small molecule is active just by the G12C mutation in KRAS and seems to work in lung cancer only." (PMID 32436621, 2020). "In addition, inactivation of the tumor suppressor gene LKB1 and activation of the KRAS oncogene greatly influence both lung cancer formation and growth and the risk of developing brain metastases." (PMID 33411683, 2020). "We only used one lung cancer cell line, A549, with KRAS mutation." (PMID 33276627, 2020). "KRAS mutation occurs in several malignancies such as colorectal, pancreatic and lung cancer." (PMID 32945604, 2020). "Similarly, in vivo analyses of PIERCE1 depletion in the KRAS mutation-related lung cancer mouse models revealed the suppressive effect of PIERCE1 knockout in urethane- and KRASG12D-induced lung tumorigenesis with decreased pAKT levels observed in the tumors." (PMID 32728173, 2020). "In contrast, in lung cancer cells with a KRAS-mutation during the epithelial-to-mesenchymal transition, MEK inhibition activates the FGFR, so it has been reported that cotreatment of FGFR-TKIs and MEK inhibitors effectively inhibits cancer cell survival and tumor growth." (PMID 33092268, 2020). "KRAS is the most common driver mutation in lung cancer, and is highly co-occurrent with KEAP1 and STK11 mutations, NOTCH1 has a putative role in skin cancer, loss of PTEN is the most common genomic alteration in glioblastoma, and DNMT3A has been associated with leukemia and myelodysplasia." (PMID 32374727, 2020). "Together with the finding that the growth of KRAS‐mutated cancers, including pancreatic and lung cancers, is strongly dependent on glutamine metabolism, this study suggests inhibition of glutamine uptake as a potential therapeutic target in KRAS‐mutated various human malignancies." (PMID 31709772, 2020). "In addition, researchers utilising a KrasG12D-driven lung cancer murine model with genetic deficiency for IL-6 reported that the presence of oncogenic KRAS mutation leads to a reduction in tumour growth and improved survival." (PMID 33116132, 2020). "KRAS/FSTL5 double mutations can desensitize KRAS mutant lung cancer cells to XPO1 inhibitors." (PMID 33178014, 2020). "A recent review reported additional potential biomarkers that are associated with brain metastasis from lung cancer, including the epidermal growth factor receptor, KRAS, anaplastic lymphoma kinase rearrangements, single-nucleotide polymorphisms, miroRNAs, and others." (PMID 31226155, 2019). "Epigenetic alterations may drive the formation of lung cancer by sensitizing cells to KRAS mutation." (PMID 30872662, 2019). "For example, STAT3 is frequently activated and plays oncogenic roles in non-small cell lung adenocarcinomas with the context of EGFR driver mutations, whereas low STAT3 level correlate with increased malignant progression and poor prognosis in lung cancer patients with KRAS mutations." (PMID 31296870, 2019). "Moreover, BTK inhibition re-sensitized lung cancer cells to either EGFR-targeted or SOC chemo-therapies disregarding EGFR/KRAS mutational status." (PMID 31200752, 2019). "KRAS is frequently mutated in patients with lung cancers, resulting in low survival rates." (PMID 31484165, 2019). "In addition, human KRAS‐mutant lung cancer cell lines harboring NF1 mutations (i.e., H2030 and H2347) showed marked sensitivity to glutaminase and PSAT1 inhibition, while those with WT NF1 (i.e., H23, H2009, and H1792) displayed less sensitivity." (PMID 31036704, 2019).
lung cancer (continued). "In this case, GEM models provide an ideal system in which to study the contribution of individual mutations to each step of tumor initiation and progression without the complications of mutagen-induced genome hypermutation as is common in KRAS-mutated human lung cancer cells." (PMID 31452510, 2019). "Thus our results clearly confirm the observation from previous studies that EGFR mutations are more prevalent than KRAS in Chinese lung cancer patients." (PMID 31369215, 2019). "Notably, EGFR or KRAS mutated lung cancer accounts for a significant subgroup of NSCLC, especially in adenocarcinoma." (PMID 31088477, 2019). "The impact of EGFR and KRAS mutations in Brazilian lung cancer remains poorly explored." (PMID 30824880, 2019). "Investigators have found that lung cancer patients frequently have somatic mutations in KRAS." (PMID 30997737, 2019). "Therefore, targeting STAT3 is considered a potential strategy for overcoming EGFR-TKI resistance associated with KRAS and T790 M mutations in lung cancers." (PMID 31619200, 2019). "Despite the extensive knowledge on the role of KRAS mutations in the pathogenesis of lung cancer, little is known about the role of KRAS-dependent signaling in regulating normal human airway epithelial function or the impact of cigarette smoke exposure on KRAS activation." (PMID 31399087, 2019). "KRAS is known to be mutated in pancreatic, colon and lung cancers." (PMID 30755180, 2019). "The most frequent level 2 variants were KRAS mutations in lung cancer." (PMID 30658646, 2019). "Moreover, the spliced RNA surrogate signatures of platelets were also found to be associated with the tumor tissue molecular subtype, such as EGFR and KRAS mutations in lung cancer and HER2 and MET amplifications in BC with 85–95% accuracy rates, respectively." (PMID 31705785, 2019). "Around half of KRAS-mutant lung cancer patients also carry LKB1 mutations, therefore, it will be important to test whether KRA-533 is also effective for the treatment of KRAS-mutant lung cancers with LKB1 mutation or loss." (PMID 30971271, 2019). "Indeed, the recent identification of dependencies borne through common co-occurring mutations provide an appealing strategy to target KRAS-mutant lung cancer." (PMID 31519898, 2019). "Interestingly, APC mutations in lung cancer co-occurred with KRAS mutations in NSCLC, including adenocarcinoma and SCCs26." (PMID 31372243, 2019). "Notably, 86% of the KRAS codon 12 mutations in COSMIC (12 out of 14) were found in typically KRAS-driven cancers like pancreatic, colon and lung cancer." (PMID 31189880, 2019). "Besides, recent data suggest that ALK rearrangements occur more frequently in younger NSCLC patients compared to older patients with lung cancer, whereas KRAS mutations appear to be less frequent in the younger patient cohort." (PMID 31386689, 2019). "For mechanism, AZ628 and BP-1-102 combination markedly abrogated MEK/ERK signaling pathway activation in KRAS-mutant lung cancer cells suggesting the combination of RAF and STAT3 inhibitors is an effective therapy for treating lung cancer cells harboring KRAS mutations." (PMID 31484165, 2019). "Indeed, KRAS mutations are usually detected in colorectal, pancreatic, biliary tract, and lung carcinomas, NRAS mutation in malignant melanomas, and HRAS mutation in head and neck carcinomas." (PMID 31803624, 2019). "Considering the prevalence of mutations in lung cancer and subsequent heterogeneous outcomes, we hypothesize that there are additional prognosis markers for patients with KRAS mutations, which may be possibly based on unseen traits of the gene." (PMID 29504894, 2018).
lung cancer (continued). "The results here may be clinically relevant given the interest in personalized, targeted therapies that are currently in use in lung cancer such as use of tyrosine kinase inhibitors for patients with KRAS mutations observed in many NSCLC patients." (PMID 30359271, 2018). "The best characterized driver mutations for lung cancer are KRAS, EGFR, ALK, ROS1, BRAF, and MET." (PMID 29734788, 2018). "Using A549 cells as a representative lung cancer cell line with KRAS mutations, we next determined whether the observed growth inhibition was due to apoptosis or necrosis." (PMID 29440631, 2018). "HHT may be a potent therapeutic drug against lung cancer associated with KRAS mutations through direct killing of cancer cells and indirect influencing immune microenvironments." (PMID 29844447, 2018). "Thus, KRAS mutated tumors were highly sensitive to drugs inducing oxidative stress, while antioxidants were shown to accelerate KRAS mutated lung cancer progression in mice." (PMID 29507676, 2018). "Positive correlation between KRAS mutation and IL-17 levels was also found in lung cancer patients." (PMID 30135516, 2018). "In lung cancer, the KRAS G12C mutation provides a striking example of the potential for ‘alignment’ of mutation and selection: the likelihood of the KRAS G12C mutation is increased by smoking, but in addition it is also selectively advantageous above other common KRAS mutations in the disease." (PMID 29748584, 2018). "Additionally, in KRAS-driven lung cancer, acquired resistance to KRAS suppression was associated with increased YAP activity." (PMID 30353028, 2018). "While the relationship between FDG uptake and EGFR mutations in NSCLC has previously been noted to have contradictory results, and one notable study has shown that the KRAS mutations in lung cancer showed significantly higher FDG uptake than wild type (WT) cancer." (PMID 28881771, 2017). "Next, we sought to determine whether FOXA3 or SPDEF recapitulates the in vivo function in human lung cancer cells that harbor a KRAS mutation." (PMID 28255028, 2017). "Corresponding KRas mutations frequently occur in human lung cancer." (PMID 29118048, 2017). "PIK3CA mutations co-exist mostly with KRAS mutations in lung cancer." (PMID 28212572, 2017). "Moreover, they detected mutated KRAS in the normal pulmonary tissue parenchyma excised from patiensts with lung cancer." (PMID 28199989, 2017). "KRAS-mutated lung cancer cell clones were stably silenced for LSD1 expression." (PMID 28860622, 2017). "KRAS mutation is fairly common, particularly in pancreas, colon, thyroid and lung cancers." (PMID 28422714, 2017). "Thus, we designed a meta-analysis to evaluate the diagnostic value and prognostic significance of a KRAS proto-oncogene, GTPase (KRAS) mutation for lung cancer patients." (PMID 28415658, 2017). "In the present case, the mutation in KRAS may have played a pivotal role in the metastasis of lung cancer." (PMID 28950878, 2017). "Mutations in KRAS are detected in up to 30% of lung cancer cases." (PMID 29137294, 2017). "First, we screened gene-expression data from in vitro and in vivo experimental systems of epithelial and mesenchymal origin with either wild-type or mutant KRAS allele (human immortalized bronchoepithelial cells, KrasLSLG12D/+ mouse embryo fibroblasts and a mouse model of Kras-driven lung cancer)." (PMID 28220783, 2017).
lung cancer (continued). "More recently, studies have suggested that the prognostic impact of KRAS mutation could be related to the presence of concurrent mutations such as STK11 that could define an aggressive subtype of lung cancer." (PMID 28445990, 2017). "This raises the possibility that heterogeneous adaptive responses could exist in KRAS mutant lung cancer depending on the status of co-mutated tumor suppressors, further complicating the development of a rational co-targeting strategy." (PMID 28154798, 2016). "Left-side lung cancer was more common in female patients carrying the KRAS mutation." (PMID 26739511, 2016). "ATM loss also enhances the sensitivity of KRAS- or BRAF-mutant lung cancer cells to MEK inhibition." (PMID 27922010, 2016). "In terms of novel, pharmacologically actionable targets, nitric oxide synthases (NOS) have been implicated in the etiology of KRAS-driven cancers, including lung cancer, and small molecular weight NOS inhibitors have been developed for the treatment of other diseases." (PMID 27285753, 2016). "Our data using KRAS-mutated lung cancer cell lines may suggest the translational importance of this mechanistic link in clinical lung cancer tissues." (PMID 27846317, 2016). "KRAS is the most commonly mutated isoform in human cancers, and is well known to both initiate and maintain a wide spectrum of cancers, but especially pancreatic, colorectal, and lung cancers." (PMID 27911940, 2016). "Of the 1033 lung cancer patients, 13 females and 40 males harbored KRAS mutations." (PMID 26739511, 2016). "The role of KRAS mutation as a prognostic factor is controversial in lung cancer." (PMID 27517148, 2016). "Our lung cancer panel of PD-L1-high cell lines included three squamous cell carcinomas without any known oncogenic driver mutations and one large cell carcinoma with a KRAS (Q61H) mutation." (PMID 27846317, 2016). "Nevertheless, clinical trials targeting KRAS mutations in lung cancer have been disappointing." (PMID 27626312, 2016). "In lung carcinomas, KRAS mutations are more common in smokers." (PMID 27655296, 2016). "In lung cancer, the KRAS and EGFR mutations are exclusive and rarely co-exist in the same patients." (PMID 26126624, 2015). "The KRAS gene also mutated exclusively with EGFR in lung cancers." (PMID 26212640, 2015). "However, despite numerous studies, the mechanism by which mutated KRAS exerts its effects in lung cancer is unclear." (PMID 26452035, 2015). "By exploring the signaling network of human lung ADs harbouring a KRAS mutation, this study identified new potential therapeutic targets for this group of patients which provide initial findings on the elucidation of a KRAS to in lung cancers." (PMID 26468985, 2015). "LDHB expression was found to correlate with both KRAS genomic copy number gains and KRAS mutations in lung cancer, which might explain why KRAS-mutant lung tumors are highly dependent on glycolysis for proliferation." (PMID 25973606, 2015). "The vast majority of the KRAS mutations reported in lung cancer patients are transversions." (PMID 25222473, 2014). "Furthermore, the various specific KRAS mutations seen in lung cancer in our patient group were similar to those previously reported." (PMID 25313136, 2014). "Additionally, KRAS mutations are found in 15-30% of lung cancers and are presently undruggable, although KRAS inhibitor are being developed." (PMID 24955213, 2014).